PTGS2 (prostaglandin-endoperoxide synthase 2)
Diseases named in the same sentence as PTGS2 in open-access papers (continued):
Sharing a sentence is not in itself a finding about the gene and the disease.
mycobacterial infection (1 paper, 2022). "Moreover, PTGS2 (COX-2), which is involved in PGE2 production after mycobacterial infection, causes a dysfunctional immune response that favors the survival and replication of mycobacteria by inducing the development of Th17 cells." (PMID 35821058, 2022).
nephrosclerosis (1 paper, 2023). Hardening of the kidney due to infiltration by fibrous connective tissue (fibrosis), usually caused by renovascular diseases or chronic hypertension. "Three SNPs in PTGS2 (coding for COX2) were associated with nephrosclerosis." (PMID 36690661, 2023). "The addition of three variants, namely PTGS2 rs4648268, PTGES3 rs2958155 and PTGES3 rs11300958, to a predictive model for CV events containing classic risk factors in nephrosclerosis patients, significantly enhanced its statistical power (AUC value increased from 78.6 to 87.4%, p = 0.0003)." (PMID 36690661, 2023). "We aimed to determine whether genetic variability represented by 38 tag-SNPs in genes of the cyclooxygenase pathway (PTGS1, PTGS2, PTGES, PTGES2 and PTGES3) leading to prostaglandin E2 (PGE2) synthesis, modified CV traits and events in 493 nephrosclerosis patients." (PMID 36690661, 2023).
ocular sarcoidosis (1 paper, 2023). A leading cause of inflammatory eye disease is sarcoidosis. "The following risk loci were observed for ocular sarcoidosis: rs2206593 near PTGS2 (p = 0.0096; OR = 2.20), and two variants near IL18, however with opposite directionality: rs1946518 (p = 0.006; OR = 1.61) and rs189667 (p = 0.004; OR = 0.59)." (PMID 37621457, 2023).
oncocytoma (1 paper, 2007). "CDH1 hypermethylation levels were significantly higher in ccRCC compared to chRCC and oncocytoma (p = 0.00016 and p = 0.0034, respectively), whereas PTGS2 methylation levels were significantly higher in ccRCC compared to pRCC (p = 0.004)." (PMID 17645803, 2007).
Oral leukoplakia (1 paper, 2015). A thickened white patch on the oral mucosa that cannot be rubbed off. "PTGS2 protein levels in oral leukoplakia are also greater than in the normal tissue." (PMID 26110572, 2015).
Osteoblastoma (1 paper, 2013). A rare benign bone-forming neoplasm usually arising from the spine. "Indeed, Wnt/beta-catenin target genes involved in bone metabolism, such as BMP2, BMP4, PTGS2 and MMP16, showed high expression levels in osteoblastoma." (PMID 24236197, 2013).
pelvic inflammatory disease (1 paper, 2025). Pelvic inflammatory disease (PID) is an acute or chronic inflammation in the pelvic cavity. "Additionally, Radix Paeoniae Rubra mitigated uterine inflammation in rats with pelvic inflammatory disease through si-PTGS2." (PMID 40380246, 2025).
prostatic diseases (1 paper, 2025). "The focus was on examining the association of certain SNPs in the PTGS1 and PTGS2 genes with prostatic diseases, as the enzymes encoded by these genes are linked to inflammation, mitogenesis, and neoplasm." (PMID 40184332, 2025).
renal tumors (1 paper, 2007). "Significant differences in methylation levels among the four subtypes of renal tumors were found for CDH1 (p = 0.0007), PTGS2 (p = 0.002), and RASSF1A (p = 0.0001)." (PMID 17645803, 2007). "In conclusion, we found that a gene panel including CDH1, PTGS2, and RASSF1A which might contribute to a more accurate detection and discrimination of the common renal tumors." (PMID 17645803, 2007).
rosacea (1 paper, 2021). A chronic erythematous skin disorder that affects the face. "Moreover, studies demonstrated the potential relationship between MLT target genes (MMP9, CCND1, EGFR, ICAM1, PTGS2, and SERPINE1) and rosacea-related key genes (IL-6, IL-1β, IFNγ, IL-17, and TNF-α)." (PMID 34899707, 2021).
SARS-CoV infection (1 paper, 2016). "Cxcr3, Ido1, and Ptgs2 were also selected based on prior interest in identifying critical mediators of the immune/inflammatory response not previously known to influence SARS-CoV infection." (PMID 27663205, 2016).
seminoma (1 paper, 2024). A radiosensitive malignant germ cell tumor found in the testis (especially undescended), and extragonadal sites (anterior mediastinum and pineal gland). "CtDNA hypermethylation at APC, GSTP1, PTGS2, p14, p16, and RASSF1A was investigated to detect seminomas and nonseminomas, with detected methylation patterns found to be similar between seminoma and nonseminomas." (PMID 38927984, 2024).
septic shock (1 paper, 2025). Shock caused by infection; frequently caused by gram negative bacteria, although some cases have been caused by other bacteria, viruses, fungi, and protozoa; characterized by fever, chills, tachycardia, tachypnea, and hypotension. "Among patients with septic shock versus those without, baseline serum levels of ACSL4, PTGS2, and LA were significantly higher in those with septic shock." (PMID 40264754, 2025).
sexual dysfunction (1 paper, 2019). Disturbances in sexual desire and the psychophysiologic changes that characterize the sexual response cycle and cause marked distress and interpersonal difficulty.
skin reaction (1 paper, 2022). "Luteolin and quercetin may be the core active ingredients of QYSLS in the treatment of EGFRI-related adverse skin reactions, and their therapeutic effects are potentially mediated through PTGS2, CCL2, and MMP9 in the IL-17 and TNF signaling pathway." (PMID 35372072, 2022).
Sleep apnea (1 paper, 2015). An intermittent cessation of airflow at the mouth and nose during sleep is known as sleep apnea. "Although our sample size was low for sleep apnea subjects, we were able to confirm the changes in PTGS2 in a separate cohort of “sleepy” patients." (PMID 25873764, 2015). "Transcript levels for 3 genes, including prostaglandin-endoperoxide synthase 2 (PTGS2), were elevated in patients with sleep apnea." (PMID 25873764, 2015). "Nonetheless, our results emphasize that PTGS2 cannot distinguish between sleepy patients with and without sleep apnea." (PMID 25873764, 2015). "In contrast, salivary PTGS2 was significantly increased in both sleep apnea patients and in the “sleepy” cohort but was not affected by acute sleep deprivation." (PMID 25873764, 2015). "Interestingly, PTGS2 was also elevated in patients with EDS but who did not have sleep apnea." (PMID 25873764, 2015).
spinal cord injury (1 paper, 2024). Penetrating and non-penetrating injuries to the spinal cord resulting from traumatic external forces (e.g., WOUNDS, GUNSHOT; WHIPLASH INJURIES; etc.). "Moreover, both in vitro acidic medium-induced and in vivo spinal cord injury (SCI)-induced upregulation of PTGS2 were substantially attenuated upon the administration of ASIC1A-related antagonists." (PMID 39627718, 2024).
urticaria (1 paper, 2025). A vascular reaction of the skin characterized by erythema and wheal formation due to localized increase of vascular permeability. "Furthermore, previous research has demonstrated a strong association between elevated PTGS2 expression and the onset of urticaria, consistent with our observations." (PMID 40901677, 2025).
Ventricular arrhythmia (1 paper, 2021). "Conditional cardiomyocyte-specific deletion of the Ptgs2 gene in adult mice reduces cardiac output, decreases exercise tolerance and increases susceptibility to induced ventricular arrhythmias." (PMID 34445793, 2021).
viral hepatitis (1 paper, 2024). An acute or chronic inflammation of the liver parenchyma caused by viruses. "Vitamin D exerts its influence on viral hepatitis through non-genomic factors, including matrix metalloproteinase, endothelial vascular growth factor, prostaglandins, PTGS2 (Cyclooxygenase-2), and oxidative stress." (PMID 39845086, 2024).
tumor (937 papers, 2000 to 2026). "These are Ccl4+Cd274+Lcn2+Ptgs2+ immunosuppressive neutrophils implicated in EMT induction in tumor cells." (PMID 40568084, 2025). "COX-2 (PTGS2 gene) is an enzyme produced in response to various stimuli and is associated with inflammation and tumor cell proliferation." (PMID 40788315, 2025). "RTT tumours deficient in Ptgs1 and Ptgs2 (Ptgs1/2) displayed reduced PGE2 levels that were comparable to those of NTT tumours and increased T cell infiltration." (PMID 39604727, 2025). "The enzyme PTGS2, which plays a crucial role in inflammation and tumorigenesis, is implicated in promoting the progression of malignancy by enhancing tumor invasiveness and evading apoptotic pathways." (PMID 38502348, 2024). "COX-2 (cyclooxygenase-2, encoded by Ptgs2 gene) has been reported as a crucial regulator of M2-like polarization in tumor-associated macrophages." (PMID 38767331, 2024). "Increased production of the bioactive lipid PGE2 downstream of aberrant cyclooxygenase 1 (COX1; encoded by Ptgs1) and COX2 (encoded by Ptgs2) activity is observed in many human tumours and is associated with cancer progression and poor patient survival." (PMID 38658748, 2024). "PTGS2 expression is upregulated in tumours following smokeless tobacco exposure, and there is ample evidence that increased PTGS2 expression in oral tissues is associated with tobacco chewing habits." (PMID 38426619, 2024). "Tumor-associated neutrophils expressing PTGS2 and PTGES can contribute to poor outcomes in GBM xenograft models." (PMID 36834607, 2023). "Among them, MMP9 was associated with macrophage M0 in 12 tumor types, PTGS2 was associated with six immune cell types among six tumor types, and TNF with seven immune cell types in five tumor types." (PMID 37033970, 2023). "COX2 (encoded by PTGS2) is a product of multiple stimuli, linked to inflammation and tumor cell growth." (PMID 36118092, 2022). "Our analysis of gene expression profiles in the tumour microenvironment identified genes implicated in inflammation or immune response, such as PTGS2 and TYK2." (PMID 36077723, 2022). "PTGS2 expression level is associated with an increase in tumor recurrence and as decrease in CRC specific survival rate." (PMID 36248436, 2022). "PTGS2 related to the proliferation, invasion, apoptosis, host immune response and angiogenesis of malignant tumors as well as tumor radioresistance is associated with the growth and survival of PCa, which has been shown to be overexpressed in malignant tumors." (PMID 35594510, 2022). "The possible involvement of cancer-associated fibroblasts (CAF) as a prevalent non-tumor source of PTGS2 in CRC led us to analyze in vitro the possible inducers of PTGS2 in primary colorectal CAF." (PMID 32168749, 2020). "Upregulation of PTGS2 is associated with increased cell adhesion, resistance to apoptosis, and tumor angiogenesis." (PMID 32328128, 2020). "COX2 is also over-expressed in human colon neoplasia and, in mouse models of intestinal neoplasia, Cox2 (Ptgs2)-deficiency attenuates tumor formation." (PMID 24694019, 2014). "PTGS2 and PCNA represent two important molecules for the progression of CC and treatment strategy and increased levels of PTGS2 were associated with enhanced tumor cell proliferation and tumorigenesis." (PMID 23865481, 2013). "Ptgs2 is associated with tumor immune evasion by regulating myeloid derived suppressor cells." (PMID 40568084, 2025).
tumor (continued). "A major subset of NFκB target genes in macrophages, including IL1B, IL12B, and TNF, is involved in pro-inflammatory processes, whereas another major subset exemplified by IL6, IL10, and PTGS2 (encoding for cyclooxygenase 2) mediates immunosuppression in homeostasis, wound healing, and neoplasia." (PMID 39416789, 2024). "Indeed, elevated PTGS2 has been implicated in enhanced angiogenesis, increased tumor invasion and reduced cell apoptosis, and inhibitors of PTGS2 have been proposed as promising therapeutic agents against cancer." (PMID 38778047, 2024). "Importantly, the reduced tumour size and increased Fe2+, PTGS2, and 4HNE levels caused by LACTB overexpression were significantly rescued by HSPA8 overexpression." (PMID 39047638, 2024). "The expression of PTGS2 in tumor tissues is linked to several key aspects of cancer progression." (PMID 39000413, 2024). "COX-2, an inducible enzyme encoded by the PTGS2 gene, can be highly induced by proinflammatory cytokines, tumor promoters, mitogens, and growth factors in various cells and thus participates in various pathological processes, such as the inflammatory response, cell proliferation and cell apoptosis." (PMID 36873535, 2023). "PTGS2 produces inflammatory prostaglandins, and the upregulation of PTGS2 is associated with the increase of cell adhesion, phenotypic changes, resistance to apoptosis and tumor angiogenesis." (PMID 35594510, 2022). "Moreover, transcript levels of genes associated with CRC susceptibility loci (e.g., Grem1 and Bmp4) and tumor development and invasion (e.g., Wnt5a, Ereg, Mmp3, Mmp13, Timp1, Saa3, Ptgs2, and Acsl4) were elevated in IL-11+ fibroblasts." (PMID 33863879, 2021). "PTGS2 (prostaglandin G/H synthase 2 precursor), expressed during inflammation and tumorigenesis, is associated with increased cell adhesion, negatively regulating intrinsic apoptosis in response to osmotic stress and resistance to tumor angiogenesis." (PMID 34585119, 2021). "Importantly, the tumor-associated aberrant expression of COX-2 is often related to epigenetic alterations affecting COX-2 gene (PTGS2) as well as other genes involved into biosynthesis and signaling of its main prostaglandin products." (PMID 30314310, 2018). "Importantly, as for Ptgs2−/− singly deficient cells, a clear shift in the inflammatory profile toward increased expression of anti-tumor immune mediators was seen in tumors formed by Ptgs1/Ptgs2−/− doubly deficient cells." (PMID 26343581, 2015). "We correlated PTGS2 (encoding COX-2) mRNA expression levels in human melanoma biopsies containing tumor, as well as stromal and infiltrating, cells with levels of mRNAs encoding various immune mediators, including those that we found to be controlled by COX-2 in the mouse models." (PMID 26343581, 2015). "ENE and grade 2 tumours are poor prognostic indicators associated with treatment resistance and an increased likelihood of spread or recurrence, emphasising the potential for targeted treatment strategies involving PTGS2 and VEGF signalling pathway genes for optimal oncological outcomes." (PMID 38426619, 2024). "Ptgs2-expressing fibroblasts around intestinal crypts exert paracrine control of tumor-inducing stem cells through the PGE2-Ptger4-Yap signaling axis, which helps drive tumorigenesis." (PMID 41210682, 2025). "The tumor microenvironment is a key inducer of PTGS2 overexpression, which arises from imbalances in transcriptional or post-transcriptional regulation, making it a promising biomarker for tumor identification." (PMID 40643495, 2025). "In normal physiological conditions, PTGS2 expression is very low, and the pro-inflammatory cytokines, growth factors, and tumor promoters can directly activate the expression of PTGS2." (PMID 40380246, 2025). "PTGS2 enhances tumor cell proliferation 32, promotes angiogenesis 33, regulates immune surveillance 34, and induces a pro-inflammatory tumor microenvironment." (PMID 40302810, 2025).
tumor (continued). "scRNA-seq also revealed the downregulation of Ptgs2 in the predominant tumor cluster 0 and an overall decrease in the immunosuppressive Cd274+ Lcn2+ Ptgs2+ neutrophil cluster 0 in the CAR-T-treated group." (PMID 40568084, 2025). "PTGS2, a ferroptosis biomarker that encodes the COX2 protein, was significantly downregulated in the tumour tissues of the DEN‐initiated HCC mouse model." (PMID 40088428, 2025). "This study is the first to demonstrate that lncRNA LOC610012 inhibits CMT cell proliferation, migration, and invasion, as well as tumor growth in vivo, by regulating the PTGS2/EP3/GSK-3β axis." (PMID 40643495, 2025). "TGF-β has also been demonstrated to induce HPGD, a prostaglandin-degrading enzyme with tumor suppressor activity that works as a catabolic antagonist for PTGS-2 activity." (PMID 40763299, 2025). "The proteins CAPS3, ICAM-1, CXCR4, and PTGS2 are key players in regulating the life cycles of tumor cells." (PMID 38502348, 2024). "Next, we verified the expression of A20/ACSL4 in the tumor by immunohistochemistry, the expression of the ferroptosis marker PTGS2, and the obvious effect of Apatinib + miR-214-3p inhibitors on tumor angiogenesis by CD34." (PMID 38370339, 2024). "The results of in vivo detection markers, including PTGS2 mRNA levels and MDA quantification, suggested that knocking down BMAL1 increased tumor cell susceptibility to ferroptosis." (PMID 38703241, 2024). "The results showed that LACTB overexpression significantly retarded tumour growth, accompanied by the elevation of Fe2+, PTGS2, and 4HNE and the downregulation of GSH." (PMID 39047638, 2024). "The relationship between IDO1 and marker genes of tumor-associated macrophages (TAMs; CCL5, CD68, and IL10), M1 (IRF5, NOS2, and PTGS2), and M2 (CD163, VSIG4, and MS4A4A) macrophages was analyzed." (PMID 39351094, 2024). "TGF-β has also been demonstrated to induce HPGD27, a prostaglandin-degrading enzyme with tumor suppressor activity that works as a catabolic antagonist for PTGS-2 activity." (PMID 39763728, 2024). "Despite its role in tumor progression, a survival analysis revealed that BC patients with a high expression level of PTGS2 had a longer survival time after established treatments." (PMID 37762335, 2023). "Emerging genetic and clinical studies have suggested that in animal models, increased expression of PTGS2 induces tumorigenesis, while inhibition of PTGS2 results in decreased tumor incidence and progression." (PMID 36795572, 2023). "We examined the gene expression involved in the resolvin E biosynthesis pathway and found that Ptgs2 was significantly increased in the normal epithelium tissues of the high tumor group (GM:F344) compared to the GM:LEW group." (PMID 37458451, 2023). "Blocking PTGS2 by celecoxib also inhibited the promoting role of AA in tumor growth in AOM/DSS mice and intestine-specific Apc−/− mice." (PMID 37041160, 2023). "Afterwards, the tumor tissues were isolated and subsequently an immunohistochemistry analysis was performed by staining Ki-67 and PTGS2, the marker for assessment of ferroptosis in vivo." (PMID 37296105, 2023). "Both PTGS2, which drives prostaglandin synthesis in the tumor microenvironment, and ADRB2 activation can increase cell migration, enhance cell survival, and promote cancer growth and metastasis." (PMID 36761962, 2023). "The analysis of tumor samples before and after radiotherapy from 32 patients affected by CC reveals that increased expression of cGAS, ATF3, and PTGS2 as well as an high density of CD8+T-cells associate with a high disease-free survival rate." (PMID 37388241, 2023). "It has also been revealed that the induction of ferroptosis in tumor cells is related to increased expression of PTGS2 and the release of PGE2." (PMID 37212877, 2023). "PTGS2 is activated and elevated in tumor tissues, and antitumour medications attempt to inhibit it through the Ub system." (PMID 37719850, 2023).